OTUD6B (OTU deubiquitinase 6B)
Diseases named in the same sentence as OTUD6B in open-access papers (continued):
Sharing a sentence is not in itself a finding about the gene and the disease.
viral infection (1 paper, 2023). "Confocal microscopy showed that more IRF3 translocated to the nucleus with overexpressing OTUD6B upon viral infection as measured using mean fluorescence intensity (MFI), the MFI value changed from 8,965 to 11,260." (PMID 37650650, 2023). "Consistently, ISG expression was higher in OTUD6B-upregulated mice, and less viral infection was detected in their lung tissue and serum than in control mice 3 days post infection." (PMID 37650650, 2023). "When viral infection was extended to 10 days, survival results showed that OTUD6B-upregulated mice were more resistant to VSV infection than control vector-injected mice." (PMID 37650650, 2023). "We also examined OTUD6B protein levels during viral infection and found that it increased and peaked at 8 h post infection, suggesting that OTUD6B may execute an antiviral function during viral infection." (PMID 37650650, 2023). "Collectively, these findings suggested that OTUD6B can inhibit viral infection." (PMID 37650650, 2023). "Furthermore, we found that human OTUD6B enhances type I IFN antiviral immune response in mice upon viral infection." (PMID 37650650, 2023). "Whether human OTUD6B plays a similar role in viral infections remains elusive." (PMID 37650650, 2023).
Williams syndrome (1 paper, 2021). "Herein, we describe novel genetic defects of OTUD6B, 8q21.3 microdeletion compounded with a point mutation of the gene, in a patient with ID and Williams syndrome-like phenotypes." (PMID 34680978, 2021). "In conclusion, we suggest that Williams syndrome-like phenotypes, namely, periorbital edema, hanging cheek, and long and smooth philtrum represent an expanded range of phenotypes of OTUD6B-related ID." (PMID 34680978, 2021). "We suggest that Williams syndrome-like phenotypes, namely, periorbital edema, hanging cheek, and long and smooth philtrum represent expanded phenotypes of OTUD6B-related ID." (PMID 34680978, 2021).
tumor (18 papers, 2014 to 2026). "Correlation analyses using data from the TIMER2 database revealed that OTUD6B expression was positively associated with the level of M1-like macrophage infiltration in most tumor types while it was negatively correlated with M2-like macrophage." (PMID 36052059, 2022). "Overall, we discovered that OTUD6B was an important regulator for tumor-derived missense mutated pVHL." (PMID 35110537, 2022). "A combination of Otud6b, Stk39 and Lgals8 gave an AUC of 0.868 (95% CI 0.744-0.968, p < 0.001) for pre-diagnostic sera and 0.871 for sera derived from tumor bearing mice (95% CI 0.744-0.976, p < 0.001) with a sensitivity of 0.75 and specificity of 0.8." (PMID 24886063, 2014). "Similarly, in ccRCC tumor cells with pVHL missense mutations, OTUD6B inhibited ccRCC migration by regulating pVHL/HIF-2α; low levels of OTUD6B predicted a higher pathological stage and shorter OS in ccRCC patients." (PMID 41050073, 2025). "Considering a half of the tumor‐driven pVHL mutations harbor in α domain of pVHL, which interferes with its ability to bind elongin C and leads to the loss of pVHL protein stability, we propose that OTUD6B overexpression resists HIF‐1α accumulation in tumor cells with pVHL α domain mutations." (PMID 32328410, 2020). "In the present study, we found that in most tumor types, OTUD6B expression was negatively linked with M1-like macrophage infiltration cells, while it was positively linked with M2-like macrophage infiltration cells, indicating that OTUD6B may play a role in macrophage polarization." (PMID 36052059, 2022). "OTUD6B is a new identified ovarian-tumor (OUT) deubiquitylating enzyme families, and a biomarker in most cancer." (PMID 40034749, 2025). "To confirm that CD8+ T cells mediate the tumor-supressing effects of Otud6b-expressing MC38 cells in C57BL/6J mice, we depleted CD8+ T cells using administration of anti-CD8 antibody in the CRC liver metastasis model." (PMID 40651961, 2025). "Immunofluorescence (IF) assay revealed that Otud6b expression in tumor cells was positively correlated with CD8+ T cell infiltration in liver metastasis." (PMID 40651961, 2025). "In the hypoxic tumor microenvironment, HIF-1α promotes angiogenesis and tumor invasion and directly promotes OTUD6B transcription." (PMID 41050073, 2025). "The results showed that the tumor growth rate of normal LUAD mice was significantly greater than that of LUAD mice with OTUD6B knockdown, as evidenced by the growth curve." (PMID 38880876, 2024). "The results showed that the tumor tissues of normal LUAD mice were more malignant than those of LUAD mice with knocked down OTUD6B expression." (PMID 38880876, 2024). "Although OTUD6B has been reported to promote tumor progression, the specific substrate OTUD6B, a member of the deubiquitinase family, has not been studied." (PMID 38880876, 2024). "In ESCC patient‐derived xenograft (PDX) models, the inhibitory effect of ATRA on tumor growth was also observed, and the level of OTUD6B was positively correlated with β‐TrCP and negatively correlated with SNAIL." (PMID 37038094, 2023). "In ESCC tumor samples, OTUD6B expression is positively correlated with β‐TrCP and its lower expression associates with a poor prognosis." (PMID 37038094, 2023). "In our present study, we further explored the impacts of OTUD6B on the stability of tumor-driven pVHL mutants." (PMID 35110537, 2022). "The ability of OTUD6B to inhibit tumor proliferation was further verified in vivo in a nude mouse model." (PMID 36052059, 2022). "Here we revealed that OTUD6B functioned as a tumor suppressor in ccRCC, which expands our understanding on the functional roles of the OTU DUBs family." (PMID 35110537, 2022). "Ovarian-tumor (OTU) domain-containing protein 6B (OTUD6B), one of newly identified OTU deubiquitylating enzyme families, is proved to be associated with tumor progression." (PMID 36052059, 2022).
tumor (continued). "OTUD6B is able to interact with wild type pVHL and tumor-derived pVHL missense mutants, except for pVHL I151T, and decrease their ubiquitylation and proteasomal degradation in ccRCC cells." (PMID 35110537, 2022). "This study provides direct evidence to identify OTUD6B as a tumor suppressor for HCC metastasis, and also couple OTUD6B to the cancer‐related pVHL‐HIF signaling pathway." (PMID 32328410, 2020). "However, upon depletion of CD8+ T cells, the Otud6b overexpression group exhibited an increased number of liver metastasis than the control group, reversing the tumor-suppressive effect of Otud6b in immunocompetent mice." (PMID 40651961, 2025). "We utilized flow cytometry analysis on C57BL/6J mice to investigate whether CD8+ T cells changed in immunocompetent mice and found an increased number of CD8+ T cells in tumor tissue of C57BL/6J mice exhibiting high Otud6b expression." (PMID 40651961, 2025). "OTUD6B inhibited tumor metastasis through CXCL11-CXCR3 axis." (PMID 40651961, 2025). "Otud6b reduced the number of tumor nodules and the tumor area." (PMID 40651961, 2025). "A549 xenografts revealed that OTUD6B deletion can slow down tumour growth." (PMID 38880876, 2024). "In addition, we subcutaneously inoculated normal LUAD cells (vector-A549) and OTUD6B-overexpressing LUAD cells (OTUD6B-A549) into nude mice to construct subcutaneous tumor models." (PMID 38880876, 2024). "The expression of OTUD6B has been reported to have a significant impact on tumor progression." (PMID 38880876, 2024). "Furthermore, we evaluated OTUD6B expression at different tumor stages according to the World Health Organization (WHO) and found that it was highly expressed in most advanced tumors including LUAD, ESAD, STAD, BLCA, BRCA, COADREAD, LIHC, and OSCC." (PMID 36052059, 2022). "Second, OTUD6B is highly expressed and correlated with poor prognosis in many tumor types; while we have validated some mechanisms, its specific mechanism is still unknown." (PMID 36052059, 2022). "Indeed, both OTUD6B and LIN28B inactivation led to a significant reduction of MM tumor size, weight and volume and IHC analyses of the respective tumors showed an induction of apoptosis in both OTUD6B and LIN28B depleted tumors." (PMID 36059274, 2022). "In ccRCC tumor cells with pVHL missense mutations, at absence of OTUD6B, the binding of elonginC and pVHL is disrupted, and pVHL is ubiquitylated and degraded." (PMID 35110537, 2022). "To investigate the potential biological pathways in which OTUD6B may be involved in affecting tumor genesis and progression, we conducted GSEA in 33 tumors from TCGA." (PMID 36052059, 2022). "We found that OTUD6B depletion significantly enhanced the tumor metastases of lung and liver." (PMID 32328410, 2020). "In contrast, OTUD6B may be a tumor suppressor factor in HCC and ccRCC." (PMID 41050073, 2025). "In one study using TgMMTV-neu mouse, three early-stage tumor antigens (PDHX, STK39, and OTUD6B) were identified by serological analysis of cDNA expression libraries (SEREX) screen that could serve as superior antigen targets for the inhibition of tumor growth." (PMID 37513965, 2023). "Importantly, we found that ATRA treatment could efficiently suppress ESCC tumor initiation and progression through promoting the translation of OTUD6B." (PMID 37038094, 2023). "Functionally, OTUD6B promotes CRC cell proliferation, migration, and invasion in vitro and enhances tumor growth and liver metastasis in vivo." (PMID 42056075, 2026). "Mechanistically, in the hypoxic tumor microenvironment, HIF-1α promotes angiogenesis and tumor invasion and directly promotes OTUD6B transcription." (PMID 41050073, 2025). "OTUD6B overexpression significantly enhanced CRLM, manifested by increased tumor nodules and tumor area." (PMID 40651961, 2025). "The results showed that mice inoculated with OTUD6B-overexpressing LUAD cells (OTUD6B-A549) had significantly faster tumor growth and greater tumor weight than did those in the normal group." (PMID 38880876, 2024).
tumor (continued). "Additionally, ESR1, OTUD6B, USP2, and USP37 showed a positive correlation with risk scores, while USP22 exhibited a significant negative correlation with risk scores (r = -0.7, p < 0.0001), suggesting a potential role for these genes in ESCC tumor progression and patient prognosis." (PMID 39742278, 2024). "We subcutaneously inoculated nude mice with the normal LUAD cell line A549 (shNC) or the LUAD cell line with OTUD6B knockdown (shOTUD6B-1, shOTUD6B-2) to construct mouse LUAD models, and the tumor-bearing mice were divided into three groups." (PMID 38880876, 2024). "An increased level of OTUD6B expression predicted a high level of TAM infiltration and generated an immunosuppressive microenvironment, which provides a possible target for tumor immune therapy." (PMID 36052059, 2022). "Therefore, OTUD6B may provide a pathway for tumor immunotherapy toward these targets." (PMID 36052059, 2022). "Unexpectedly, Otud6b-overexpressing C57BL/6J mice exhibited tumor suppression rather than progression." (PMID 40651961, 2025). "Besides, Otud6b knockdown inhibited the amount and activation of CD8+ T cells in C57BL/6J mice tumor tissue." (PMID 40651961, 2025). "As a result, the tumor suppressive effects of ATRA require the existence of OTUD6B transcripts, which suggests that OTUD6B transcript level can serve as a biomarker to predict whether ATRA would benefit specific ESCC patients." (PMID 37038094, 2023). "Importantly, all‐trans retinoic acid is found to promote OTUD6B translation and thus suppresses ESCC tumor growth and enhances the response of ESCC tumors to anti‐PD‐1 immunotherapies." (PMID 37038094, 2023). "Importantly, all‐trans retinoic acid (ATRA) is found to promote OTUD6B translation and thus suppress ESCC tumor growth and enhance the response of ESCC tumors to anti‐PD‐1 immunotherapies." (PMID 37038094, 2023). "Overall, hypoxia‐induced expression of OTUD6B increased stability of pVHL, which recognizes hydroxylated or SUMOylated HIF‐1α under hypoxia, and leads to rapid polyubiquitylation and proteasomal degradation of HIF‐1α and suppressed tumor metastasis." (PMID 32328410, 2020). "We observed that OTUD6B knockdown had no influence on tumor growth, but the number of blood vessels indicated by CD31 expression was significantly increased in the xenograft tumors with OTUD6B knockdown, compared with the negative control." (PMID 32328410, 2020). "In HCC cells, the knockdown of OTUD6B promoted the migratory ability and EMT of HCC cells but did not affect the proliferative ability of the cells; in the HCC nude mouse model, knockdown of OTUD6B also promoted angiogenesis and lung metastasis but did not affect tumor growth." (PMID 41050073, 2025). "The ATRA‐mediated enhancement of tumor response to anti‐PD‐1 treatment relies on the existence of OTUD6B mRNA, since in OTUD6B‐knockdown ESCC tumors, ATRA could not improve the effects of anti‐PD‐1 immunotherapy." (PMID 37038094, 2023). "We found that CD276 and VEGFA expression was significantly positively correlated with the expression of OTUD6B in nearly all types of cancer, so were the immune checkpoint inhibitor genes HMGB1 and TLR4, suggesting that OTUD6B may provide some help for tumor immunotherapy through these targets." (PMID 36052059, 2022). "In addition, we discovered that OTUD6B mRNA level was in a significant decreasing trend with the development of ccRCC pathological stage (including I–II, III–IV stage or M0, M1 stage) in tumor tissue with or without VHL mutation." (PMID 35110537, 2022). "In this study, we show that ovarian‐tumor (OTU) domain‐containing protein 6B (OTUD6B), a member of OTU deubiquitylating enzyme family, inhibits the activation of HIF pathway via maintaining the protein stability of pVHL and thus functions as a tumor suppressor for HCC metastasis." (PMID 32328410, 2020). "However, the investigation did not examine the role of OTUD6B in tumor immunity." (PMID 40651961, 2025).
tumor (continued). "Additionally, the results of expression analysis on the data of Chinese Human Proteome Project (CNHPP) (110 paired tumor and nontumor tissues of clinical early‐stage HCC) showed consistently upregulation of protein level of OTUs (including OTUD7B, OTUD6B, ALG13, OTUB1, OTULIN) in HCC tissues." (PMID 32328410, 2020).
cancer (15 papers, 2014 to 2026). A tumor composed of atypical neoplastic, often pleomorphic cells that invade other tissues. "OTUD6B is another member of the OTU family of DUBs that has been linked to the regulation of several cellular processes contributing to cancer progression, including cell proliferation, apoptosis, and metastasis." (PMID 38880876, 2024). "Immune scores were significantly associated with OTUD6B expression in 19 of 33 cancers, and stromal scores were significantly associated with OTUD6B expression in 12 of 33 cancers, respectively." (PMID 36052059, 2022). "OTUD6B expression was significantly correlated with MSI in 10 out of 33 cancer types; it was positively associated with MSI in five (KIRC, SARC, CESC, STAD, LUSC) and negatively associated with MSI in five (DLBC, COAD, COADREAD, HNSC, PRAD) types of tumors respectively." (PMID 36052059, 2022). "USP35, USP36, USP37, USP47, USP49, and OTUD6B play crucial roles in cancer progression and chemoresistance across various cancers, including NSCLC." (PMID 41399373, 2026). "As such, OTUD6B is an attractive new cancer-specific therapeutic target, especially in hard-to-treat cancers such as TNBC." (PMID 39789388, 2025). "Pan-cancer analysis revealed that high OTUD6B mRNA expression was observed in 10 tumors, including COAD and READ." (PMID 40651961, 2025). "As a deubiquitinase that supports KIFC1 expression, allowing pseudo-bipolar cell division and survival of cancer cells with centrosome amplification, OTUD6B has potential as a novel target for cancer-specific therapies." (PMID 39789388, 2025). "We used immunohistochemistry to detect the expression levels of RIPK1 and OTUD6B in the cancer tissues of 119 patients with LUAD and analyzed the correlation between them by statistical methods." (PMID 38880876, 2024). "While the antitumor effects of OTUD6B have been reported in multiple cancers, such as breast, liver, and pancreatic adenocarcinomas, its expression in LUAD and impact on patient prognosis have yet to be established." (PMID 38880876, 2024). "The staining results of each pair of tissues were immunohistochemically scored, and we found that OTUD6B was significantly more highly expressed in cancer tissues than in paracancerous tissues." (PMID 38880876, 2024). "Consistently, a drug sensitivity prediction analysis using the genomics of drug sensitivity in cancer database found that the sensitivity of OTUD6B‐knockdown cells to ATRA was likely to be significantly lower than that of control cells." (PMID 37038094, 2023). "In this study, OTUD6B expression has been unraveled to be positively correlated with most of the 47 immune checkpoint genes in almost all cancers, such as CD276, VEGFA, HMGB1, and TLR4." (PMID 36052059, 2022). "The profiles of OTUD6B expression in multiple cancers were analyzed using The Cancer Genome Atlas (TCGA) database." (PMID 36052059, 2022). "To sum up, we detected an oncogenic effect of OTUD6B and suggested its potential as a prognostic biomarker in pan-cancer." (PMID 36052059, 2022). "In the present study, we evaluated the expression of OTUD6B in various cancers, as well as its role of prognosis and immunity value using multiple public databases." (PMID 36052059, 2022). "Our results provide new insights into the remarkable functional role of OTUD6B and can be used as a potential target for future therapeutic development in various cancers." (PMID 36052059, 2022). "USP36, USP37, USP47, and OTUD6B exert its oncogenic effects by stabilizing key oncoproteins, such as cellular myelocytomatosis oncogene (c-Myc), 14-3-3γ, Snail, and β-catenin, thereby promoting cancer cell proliferation, migration, and invasion 27-32." (PMID 41399373, 2026). "Overall, these data suggest that cancer cells with centrosome amplification depend upon the catalytic activity of OTUD6B to safely execute cell division, at least in part through the role of OTUD6B in protecting KIFC1, which facilitates centrosome clustering." (PMID 39789388, 2025).